HMGB1 (high mobility group box 1)
Diseases named in the same sentence as HMGB1 in open-access papers (continued):
Sharing a sentence is not in itself a finding about the gene and the disease.
hepatocellular carcinoma (continued). "More broadly, HMGB1 promotes mitophagy to eliminate damaged mitochondria before apoptotic signals can propagate; the PARP1/HMGB1 node acts as a molecular switch that biases cells toward autophagy over apoptosis and contributes to chemoresistance in hepatocellular carcinoma." (PMID 41465435, 2025). "Additionally, morin hydrate was shown to reverse resistance in cisplatin-resistant hepatocellular cancer HepG2DR cells by impairing poly (ADP-ribose) polymerase (PARP-1)/ high mobility group box 1 (HMGB1)-dependent autophagy." (PMID 39519572, 2024). "It has been shown that RAGE is significantly upregulated in hepatocellular carcinoma tissue, and treatment of hepatocellular carcinoma cells (Huh7) with HMGB1 promotes cancer cell progression from the G1 phase to the S phase, accelerating cell division and proliferation." (PMID 38529373, 2024). "Furthermore, miR-142-3p attenuated metastasis by inhibiting HMGB1 expression in hepatocellular carcinoma cells." (PMID 36635290, 2023). "Moreover, HMGB1 fosters hepatocellular carcinoma immune evasion by promoting regulatory B-cell expansion." (PMID 37110415, 2023). "High-mobility group box 1 (HMGB1) is a conserved nuclear chromatin-binding protein that may have important tumor-promoting activity in several cancers, including hepatocellular carcinoma (HCC)." (PMID 37345014, 2023). "Suppressing the expression of the high mobility group box 1 (HMGB1) gene could reduce glutamine metabolic activity in hepatocellular carcinoma cells and significantly enhance the response of HCC cells to PD-L1 antagonists." (PMID 36497182, 2022). "Similarly, ablation of high mobility group box 1 (HMGB1) protein in hepatocellular carcinoma subjected to hypoxia promoted mitochondrial biogenesis and reduced ATP." (PMID 35205167, 2022). "HMGB1 is a direct target of miR-320a, and the expression level of miR-320a might regulate the invasion and metastasis of hepatocellular carcinoma (HCC) cells by targeting the HMGB1 pathway." (PMID 35269471, 2022). "Moreover, HMGB1 promoted hepatocellular carcinoma progression partly by enhancing the ERK1/2 and NF-κB pathways, upregulating MMP-2, and downregulating p21 via an ERK/c-Myc pathway." (PMID 35610613, 2022). "In addition, hepatocellular carcinoma-derived high mobility group box 1 (HMGB1) can drive M2 macrophage polarization through TLR2-dependent autophagy." (PMID 36059534, 2022). "HMGB1 is also involved in the pathogenesis of hepatic carcinoma." (PMID 34458256, 2021). "Under hypoxic conditions, the reductive stress induced by H2Se promoted cell autophagy via regulating the redox of human high-mobility group protein B1 (HMGB1), and excessive autophagy leads to autophagy-associated cell death in human hepatocellular carcinoma HepG2 cells." (PMID 34065478, 2021). "In the process of HCC, hypoxia exposure gives rise to HMGB1 expression to mediate mitochondrial biogenesis and stimulate macrophage‐derived interleukin‐6, which promotes tumor growth and enhances the invasiveness and metastasis of hepatoma cells." (PMID 32436353, 2020). "To understand whether HMGB1 may have intrinsic effects on hepatoma cell growth, we first monitored the cell growth of shLuc- and shHMGB1-ML-14a cells in vitro." (PMID 32788720, 2020). "Numerous studies have recognized the upregulation of the ERK/MAPK pathway by HMGB1 in colon carcinoma, renal cell carcinoma, liver carcinogenesis in mice, gastric carcinoma, hepatocellular carcinoma, breast adenocarcinoma (MCF-7), and alveolar basal epithelial cells adenocarcinoma (A549) cells." (PMID 32443845, 2020). "HMGB1 is highly expressed in the tumor tissue, often with enhanced cytosolic translocation, in almost all cancers including breast, colorectal, pancreatic, and hepatocellular carcinoma." (PMID 31379812, 2019).
hepatocellular carcinoma (continued). "Overexpression of HMGB1 was significantly correlated with poorer overall survival in esophageal cancer, gastric cancer, colorectal cancer, pancreatic cancer, hepatocellular carcinoma, nasopharyngeal cancer, head and neck cancer, bladder cancer, cervical cancer, and pleural mesothelioma." (PMID 31399104, 2019). "Finally, a study conducted using hepatocellular carcinoma cell lines showed that HMGB1 silencing inhibited in vitro cell proliferation, migration, invasion and ultimately led to cell apoptosis." (PMID 29472602, 2018). "Moreover, miRNA-505 suppresses proliferation and invasion in hepatoma cells by directly targeting HMGB1 has been previously reported." (PMID 28423715, 2017). "Nevertheless, this study provides preliminary evidence that potentially unfavorable combinations of polymorphisms from the HMGB1/RAGE axis could synergistically affect the onset and progression of hepatocellular carcinoma." (PMID 28187002, 2017). "One therefore could hypothesize that HMGB1 and RAGE genes are two potential candidate susceptibility genes for hepatocellular carcinoma." (PMID 28187002, 2017). "In this multicenter matched case-control study, we set out to examine the hypothesis that HMGB1 and RAGE genes are two potential candidate susceptibility genes for hepatocellular carcinoma." (PMID 28187002, 2017). "Long ncRNA MIR22HG could repressed hepatocellular carcinoma cell invasion by deriving miR-22 and targeting HMGB1." (PMID 29179461, 2017). "To test this hypothesis, we designed a multicenter case-control study and genotyped seven widely-studied polymorphisms from HMGB1 and RAGE genes among 540 hepatocellular carcinoma patients and 540 age- and gender-matched controls." (PMID 28187002, 2017). "The mutant alleles of two polymorphisms, rs1045411 in HMGB1 gene and rs2070600 in RAGE gene, had significantly higher frequencies in hepatocellular carcinoma patients than in controls (both P < 0.001), and this significance was attained even after the Bonferroni correction (P < 0.05/7)." (PMID 28187002, 2017). "This review aims to retrieve literature regarding HMGB1 from English electronic resources, analyze and summarize the role of the HMGB1 signaling pathway in hepatocellular carcinoma (HCC), and provide useful information for carcinogenesis and progression of HCC." (PMID 26393575, 2015). "In our study, calycosin downregulated HMGB1, which may be related to the antitumor mechanism of calycosin on hepatocellular carcinoma cells." (PMID 24455688, 2013). "Another marker of necrosis, the release of nuclear protein, HMGB1, was also found to be released from Con A -treated hepatoma cells, and IFN-γ could enhanced this release." (PMID 22163006, 2011). "High mobility group protein B1 (HMGB1) is most typically linked to hypoxia-induced macrophage polarization.HMGB1 is overexpressed in numerous solid tumors and has been linked to skin carcinogenesis, inflammatory responses in hepatocellular carcinoma, and colon cancer." (PMID 38655133, 2024). "Similarly, liver-specific knockout of Gpx4 accelerates diethylnitrosamine-induced hepatocellular carcinoma by releasing high-mobility group box 1 (HMGB1), recruiting myeloid-derived suppressor cells (MDSCs), and upregulating the checkpoint protein CD274 (also known as PD-L1)." (PMID 38844964, 2024). "In hepatocellular carcinoma (HCC), the competitive binding of high-mobility group box 1 (HMGB1) and RICTOR in the mTOR pathway to miR-200 family members, such as miR-429, supports tumor self-renewal, tumorigenesis, and glutamine metabolism." (PMID 39724442, 2024). "In a study on hepatocellular carcinoma (HCC), the high-mobility group box 1 gene (HMGB1) and the important molecule RICTOR in the mTOR pathway competitively bound to members of the miR-200 family, especially miR-429." (PMID 38302430, 2024). "In hepatocellular carcinoma (HCC) and gastric cancer (GC), HMGB1 facilitates tumorigenesis by inducing the polarization of macrophages toward an M2 phenotype." (PMID 38529373, 2024).
hepatocellular carcinoma (continued). "Other studies indicate that HMGB1 may be an important marker for assessing tumour staging and predicting prognosis in hepatocellular carcinoma, as HMGB1 levels in hepatocellular carcinoma were significantly higher than in chronic hepatitis, cirrhosis and healthy controls." (PMID 37298365, 2023). "Additionally, as a member of damage-associated molecular pattern (DAMP), the high-mobility group box 1 (HMGB1) has been shown to promote autophagy and induce drug resistance against docetaxel in lung adenocarcinoma and doxorubicin in hepatocellular carcinoma, respectively." (PMID 37355631, 2023). "By targeting HMGB1, miR-548b-3p and miR-320-3p suppressed hepatocellular carcinoma (HCC) cell proliferation, metastasis, and invasion while inducing apoptosis." (PMID 34073766, 2021). "However, it was still unknown whether decreased HMGB1 ameliorated the development of liver carcinoma in the murine H. hepaticus infection model." (PMID 35046917, 2021). "Furthermore, HMGB1 also links hepatocyte injury to hepatocellular carcinoma (HCC)." (PMID 35187072, 2021). "For example, TP73-AS1 can promote hepatocellular carcinoma (HCC) cell proliferation via miR-200a-dependent HMGB1/RAGE regulation, and its high expression level is significantly associated with a poorer prognosis of HCC patients." (PMID 32493915, 2020). "Therefore, we examined whether hepatoma-derived HMGB1 facilitates MCM-triggered M2 macrophage polarization." (PMID 32788720, 2020). "Unresolved inflammation maintained by release of danger‐associated molecular patterns, particularly high‐mobility group box‐1 (HMGB1), is crucial for hepatocellular carcinoma (HCC) pathogenesis." (PMID 32697038, 2020). "Through extensive analyses, our findings support this hypothesis by identifying two risk associated polymorphisms, rs1045411 and rs2070600 from the HMGB1/RAGE axis, and more importantly a joint impact of seven polymorphisms in susceptibility to hepatocellular carcinoma." (PMID 28187002, 2017). "In hepatocellular carcinoma (HCC), elevated HMGB1 released from gluconeogenic enzyme fructose 1,6-bisphosphatase (FBP1)-deficient hepatocytes triggers HSCs activation." (PMID 40761743, 2025). "HMGB1, stimulated by chemotherapeutic drugs, can be transported to the cytoplasm and promotes autophagy through activation of AMP-activated protein kinase (AMPK), which in turn causes inhibition of mTOR in hepatocellular carcinoma cells (HCC)." (PMID 38725632, 2024). "Indeed, HMGB1 has been implicated in the progression of a wide range of human cancers including NSCLC, pancreatic ductal adenocarcinoma, metastatic breast cancer, ovarian cancer, hepatocellular carcinoma, colorectal cancer, metastatic melanoma, mesothelioma, and gastric cancer." (PMID 36831371, 2023). "In hepatocellular carcinomas, PCAT1 silencing downregulates the level of high mobility group box 1 (HMGB1) and incapacitates the invasive and migratory potential." (PMID 35055115, 2022). "Regarding HMGB1 and B-cell interactions, a recent study indicated that tumor-derived HMGB1 induced the expression of TIM1+ regulatory B cells in hepatocellular carcinoma." (PMID 34617194, 2022). "As for measles virus (MV), the Edmonston strain mediated the release of type I IFNs and HMGB1 in human melanoma and CRT exposure, ATP, and HMGB1 release in hepatocellular carcinoma (HCC)." (PMID 36755812, 2022). "In hepatocellular carcinoma, TP73-AS1 promotes cell growth via a TP73-AS1/miR-200a/HMGB1/RAGE signaling axis and accelerates malignant progression through regulating microRNA-103." (PMID 35614413, 2022). "That suppresses miR‐200a to enhance hepatocellular carcinoma (HCC) cell proliferation, mediated through the HMGB1/RAGE axis." (PMID 33683827, 2021). "ROCK1nc mice also developed fewer diethylnitrosamine-induced hepatocellular carcinoma (HCC) tumours, while HMGB1 inhibition increased HCC tumour numbers." (PMID 33871359, 2021).
hepatocellular carcinoma (continued). "In hepatocellular carcinoma (HCC) tumors, HMGB1 was shown to mediate tumor growth, under hypoxic conditions, through the interaction with intracellular TLR-9 and to attract macrophages to the tumor site, resulting in increased metastasis." (PMID 34360919, 2021). "In hepatocellular cancer, miR-142-3p was shown to bind the 3′-UTR region of HMGB1 and resulted in the inhibition of proliferation and invasion of tumor cells." (PMID 33015161, 2020). "By using an in vitro cell culture model, we demonstrate an augmented inflammatory potential of murine necrotic hepatoma cells that, at least partly, relies on the RAGE/HMGB1 axis." (PMID 32697038, 2020). "Based on experimental data, HMGB1 activates RAGE signaling and induces NF-κB activation to promote cellular proliferation in hepatocellular carcinoma (HCC) cell lines." (PMID 29670673, 2018). "High-mobility group box-1 (HMGB-1), also known as amphoterin, was the earlier targeted ligand for its role in inducing TREM-1 signaling in the activation of the Kupffer cell in hepatocellular carcinomas." (PMID 30205488, 2018). "Several lines of clinical evidence suggested that HMGB1 and RAGE possessed the potentials to serve as powerful prognostic and therapeutic targets for hepatocellular carcinoma." (PMID 28187002, 2017). "Studies in growing numbers have reported the concordant over-expression of HMGB1 and RAGE in a variety of cancer types, including hepatocellular carcinoma." (PMID 28187002, 2017). "Knockdown of RAGE by specific siRNA inhibited cellular growth in the hepatocellular carcinoma cell line, Huh7, whereas the RAGE ligand, high mobility group box 1 protein (HMGB1) increased cellular proliferation." (PMID 22754344, 2012). "However, the role of HMGB1 in hepatocellular carcinoma (HCC) remains unclear." (PMID 22747650, 2012). "Similarly, in hepatocellular carcinoma (HCC), tumor-derived HMGB1 engages TLR2 on macrophages, triggering a NOX2/ROS-dependent autophagic response that drives M2 macrophage polarization, thereby creating an immunosuppressive and pro-tumorigenic niche." (PMID 41465435, 2025). "Notably, in hepatocellular carcinoma (HCC), HMGB1 drives M2 macrophage polarization via the TLR2/NOX2/autophagy axis, accelerating tumorigenesis." (PMID 41354099, 2025). "During hypoxia, HMGB1 may translocate to cytoplasm where it binds mtDNA and activates TLR9, resulting in hepatocellular carcinoma growth." (PMID 36982351, 2023). "In addition, glycyrrhizin, a commonly used HMGB1 inhibitor, significantly inhibited the expression of HMGB1 and thus c-MYC, thereby suppressing hepatocellular carcinoma." (PMID 36193082, 2022). "Moreover, morin hydrate reversed the acquired resistance of cisplatin-resistant hepatocellular cancer HepG2DR cells by impairing PARP-1/HMGB1-dependent autophagy; indeed, PARP-1 autophagy appears to be regulated by the PARylation of HMGB1." (PMID 34025826, 2021). "Interestingly, ROCK1nc mice developed fewer genotoxin-induced hepatocellular carcinoma (HCC) tumours than ROCK1wt mice, while HMGB1 inhibition concomitant with genotoxin administration increased tumour numbers." (PMID 33871359, 2021). "A study in human cervical squamous carcinoma reported that miR-22-3p causes inhibition of cell apoptosis by targeting the eIF4EBP3 gene and suppresses cell proliferation in hepatocellular carcinoma and arterial smooth muscle by regulating SP1 and HMGB1, respectively." (PMID 32411089, 2020). "Moreover, the same study showed that HMGB1 activates the TLR9 signaling pathway by binding to released mtDNA to trigger inflammation and promote tumor growth in hepatocellular carcinoma during hypoxia." (PMID 32155899, 2020). "There has been an observed reduced expression of the HMGB1 gene in chronic Hepatitis B virus (HBV) infected patients, which hypothetically could lead to impaired DNA damage repair and favor development of hepatocellular carcinoma." (PMID 32796569, 2020).
hepatocellular carcinoma (continued). "EP induces apoptosis and cell-cycle arrest in G phase in hepatocellular carcinoma cells by inhibiting the HMGB1–RAGE and AKT pathways; EP suppresses growth and invasion of gallbladder cancer cells via downregulation of HMGB1-RAGE axis." (PMID 32742812, 2020). "Data presented indicate a remarkably inflammatory capacity of necrotic hepatoma cells that, at least partly, depends on the RAGE/HMGB1 axis and may shape immunological properties of the HCC microenvironment." (PMID 32697038, 2020). "In hepatocellular carcinoma (HCC) cell lines, miR-505 negatively regulates HMGB1, increasing doxorubicin cytotoxicity in vitro via enhanced caspase 3 activity, induction of DNA damage and decreased phosphorylation of Akt, a pathway known to be closely involved in drug resistance." (PMID 31379812, 2019). "Increased expression of HMGB1 and its receptor RAGE (receptor for advanced glycation end-products) has been observed in many types of tumors, including hepatomas and prostate cancer, and coexpression of HMGB1 and RAGE correlates with tumor invasiveness and poor clinical outcome." (PMID 21448462, 2011). "Further studies showed that during hypoxia, nuclear HMGB1 translocate to the cytoplasm and binds to mtDNA, which then activates TLR9 signaling and tumor proliferation in hepatocellular carcinoma (HCC)." (PMID 35209954, 2022). "In addition, the miR-505-3p/HMGB1 axis exerted a negative impact on tumor progression in osteosarcoma, hepatocellular carcinoma, and gastric cancer." (PMID 34073766, 2021). "Other MAPK members have been upregulated by HMGB1 including cell division control protein 42 homolog (Cdc42)/Ras-related C3 botulinum toxin substrate 1 (Rac1)/mitogen-activated protein kinase kinase 6 (MKK6)/p38 that led to the proliferation of human rhabdomyosarcoma and hepatocellular carcinoma." (PMID 32443845, 2020). "High-mobility group box 1 (HMGB1) is a potential therapeutic target and novel biomarker in a variety of malignant tumors, including hepatocellular carcinoma (HCC)." (PMID 29651425, 2018). "However, the function and mechanism of HMGB1 in hepatocellular carcinoma (HCC) remain unclear." (PMID 26499944, 2016). "In the same context, evidence revealed that HMGB1 inhibitors play a significant role in limiting the chemoresistance of hepatocellular carcinoma (HCC) cells to DOX, resulting in the re-sensitization of DOX-treated HCC cells." (PMID 38931349, 2024). "Additionally, another member of MAPKs, stress-activated protein kinases (SAPK)/ c-Jun N-terminal kinase (JNK), has been shown to be upregulated due to the HMGB1-RAGE activation in glioma, murine Lewis lung carcinoma, and hepatocellular carcinoma (HCC)." (PMID 32443845, 2020). "Under hypoxic conditions, HMGB1 could mediate the binding of mtDNA and TLR9, thereby activating the protumorigenic signaling pathways to promote the growth and metastasis of hepatocellular carcinoma cells (HCC)." (PMID 35454769, 2022).